UCHL1 (ubiquitin C-terminal hydrolase L1)
Diseases named in the same sentence as UCHL1 in open-access papers (continued):
Sharing a sentence is not in itself a finding about the gene and the disease.
breast carcinoma (continued). "In addition, UCHL1 downregulates ERα by deubiquitinating and stabilizing EGFR, thus increasing tamoxifen resistance in ERα- breast cancer." (PMID 34575114, 2021). "The forced expression of UCHL1 in cervical and breast cancer cell lines that originally showed no detectable expression of endogenous UCHL1 resulted in the upregulation of 5HREp-luc reporter activity under both normoxic and hypoxic conditions." (PMID 25615526, 2015). "In summary, we found that UCHL1 possesses tumor-suppressive functions in breast tumor cells requiring its DUB activity, and is frequently silenced by promoter methylation, thus as a potential tumor marker for breast cancer." (PMID 22279545, 2012). "We further analyzed UCHL1 expression using a tissue microarray carrying 30 breast cancer tissues and paired adjacent non-cancerous tissues by immunohistochemistry." (PMID 22279545, 2012). "Result showed that UCHL1 expression was significantly reduced in breast cancer tissues compared to the adjacent noncancerous tissues (p<0.05)." (PMID 22279545, 2012). "MSP analysis showed that UCHL1 was frequently methylated in 9/10 (90%) breast cancer cell lines, well correlated with expression levels, while no UCHL1 methylation was found in two normal mammary epithelial cell lines." (PMID 22279545, 2012). "Therefore, targeting UCHL1 may restore ER levels in ER-negative breast cancer and TNBC patients and make these breast cancer patients sensitive to endocrine therapy again." (PMID 38468288, 2024). "Therefore, targeting UCHL1 in combination could represent a novel approach to restore ER level in ER– breast cancer and TNBC patients and to de novo sensitise breast cancer patients for endocrine therapy." (PMID 34497382, 2022). "Ubiquitin carboxyl terminal hydrolase L1 (UCHL1), a ubiquitin C-terminal hydrolase belonging to the deubiquitinase (DUB) family of enzymes, is highly expressed in these cancer types, and several key reports have revealed emerging and important roles for UCHL1 in breast cancer." (PMID 34497382, 2022). "Therefore, UCHL1 may serve as new oncogenic target for the treatment of ER−, TNBC and ER+ breast cancer that is resistant to endocrine therapy, or potentially as an adjuvant target to supress recurrence." (PMID 34497382, 2022). "Significant evidence now supports a role for UCHL1 as a driver of several types of breast cancers; however, this protein has until recently lacked selective and potent small-molecule inhibitors or ABPs, limiting opportunities to explore the translational potential of these findings." (PMID 34497382, 2022). "Interestingly, a recent study showed that overexpression of a de-ubiquitin enzyme termed ubiquitin C-terminal hydrolase L1 (UCH-L1) promoted Akt activation in MCF-7 breast cancer cells without altering proliferation and enhanced cellular invasion." (PMID 30359271, 2018). "In the present study, we focused on the UCHL1-HIF-1 axis and investigated whether it induced the metabolic reprogramming, antioxidant property, and radioresistant phenotype of cancer cells using murine breast cancer-derived EMT6 cells." (PMID 28761052, 2017). "A luciferase assay to monitor HIF-1 activity demonstrated that the overexpression of UCHL1, but not its deubiquitination activity-deficient mutant (UCHL1 C90S), upregulated HIF-1 activity by stabilizing the regulatory subunit of HIF-1 (HIF-1α) in a murine breast cancer cell line, EMT6." (PMID 28761052, 2017). "It is not clear from these studies whether UCHL1 modulates ER expression and TGF-β signalling simultaneously or in a context-specific manner, as the ER expression study was conducted in ER− breast cancers, whereas the regulation of TGF-β signalling study was performed only in TNBC." (PMID 34497382, 2022).
breast carcinoma (continued). "On the other hand, it has been reported that high expression of UCHL1 in TNBC cell lines facilitates cell invasion through activation of the Akt signalling pathway, and correlates with negative ER expression and overall shorter survival of breast cancer patients." (PMID 34497382, 2022).
brain injury (50 papers, 2011 to 2026). Acute and chronic (see also brain INJURIES, CHRONIC) injuries to the brain, including the cerebral hemispheres, CEREBELLUM, and brain STEM. "The concentration of UCHL1 was increased in serum and the CSF after traumatic brain injury, and it was associated with its severity and long-term outcome." (PMID 39408830, 2024). "UCHL1, which has a more specific tissue distribution than S100B, is found more exclusively in neurons and is associated with traumatic brain injury, but it was unclear whether it could play a role in BBB disorders caused by microbial factors (e.g., gp120) and drugs of abuse." (PMID 23637989, 2013). "This study also agrees with our findings that UCHL1 levels were unable to distinguish between post-game football players, emergency room patients who suffered mild traumatic brain injury and healthy controls." (PMID 39221265, 2024). "Diagnostic aids for TBI based on GFAP and another blood-based biomarker– ubiquitin C-terminal hydrolase-L1 (UCH-L1) – have recently obtained regulatory approval (Banyan Brain Trauma Indicator Test." (PMID 35717463, 2022). "Increased serum levels of UCHL-1 also correlate with a worse outcome for children after traumatic brain injury." (PMID 32987792, 2020). "Studies on adults demonstrated that increased concentrations of UCHL1 can be found in serum after traumatic brain injury." (PMID 29401475, 2018). "Recently, the U.S. Food and Drug Administration reviewed and authorized for marketing the Banyan Brain Trauma Indicators which are ubiquitin C-terminal hydrolase-L1 (UCH-L1) and glial fibrillary acidic protein (GFAP), to evaluate mTBI in adults." (PMID 29963002, 2018). "Ubiquitin C-terminal hydrolase L1 (UCHL1) is a neuron-specific enzyme recognized in traumatic brain injury patients as a marker for direct neuron injury." (PMID 27119013, 2016). "However, two serum neuromarkers, glial fibrillary acidic protein (GFAP) and ubiquitin C-terminal hydrolase-L1 (UCH-L1), have been proven as indicators of brain trauma and AIS." (PMID 38540221, 2024). "Paired data would have been beneficial in determining if UCHL1 levels could distinguish match-play and concussion within individuals." (PMID 35851288, 2022). "Research on blood-based biomarkers of traumatic brain injury (TBI) has accelerated significantly over the past decade, including UCHL1." (PMID 40141757, 2025). "Ubiquitin carboxyl-terminal esterase L1 (UCHL1) is a biomarker that has been shown to increase following traumatic brain injury but has not been investigated in concussed athletes on the sideline of athletic events." (PMID 35851288, 2022).
lung carcinoma (46 papers, 2010 to 2026). "Upregulation of UCHL1 expression was observed in bronchial biopsies of smokers compared with non-smokers, and its expression has been linked to disease outcome in lung cancer." (PMID 21283576, 2011). "Additionally, HSD11B1 and HLA-DRA linked hypertension, diabetes, and obesity; UCHL1 linked hypertension, obesity, and lung cancer; LENG8 and HSPA1L linked diabetes, obesity, and lung cancer." (PMID 36685671, 2023). "Moreover, expression levels of UCHL1 in breast and lung cancers were found to be associated with those of HIF-1α and poor prognosis in cancer patients." (PMID 25615526, 2015). "Studies have shown that UCHL1 is upregulated in lung cancers and plays a critical regulatory role in tumorigenesis." (PMID 40428124, 2025). "UCHL1 activity correlates with the poor prognosis of patients with breast and lung cancers, and a strong correlation between UCHL1 levels and HIF activity was observed in patient samples." (PMID 38808772, 2024). "We established targeted repression of UCHL1 expression in the lung cancer cell line H1299 and showed that UCHL1 directs the expression of the extracellular matrix genes COL1A1 and fibronectin." (PMID 38016026, 2023). "Aberrantly-expressed UCHL1 has been reported in breast, endometrial, ovarian and lung cancers, emerging as a potential drug target to suppress immune escape, tumor growth and metastasis." (PMID 36980544, 2023). "It has been suggested that UCHL1 is a tumor antigen capable of triggering a humoral immune response in lung cancer, thus pointing its potential as a biomarker in lung cancer." (PMID 33805973, 2021). "It has been reported that the contents of EVs collected from serum, such as miR-200, lipocalin-2, miR-505-5p, ubiquitin C-terminal hydrolase-L1 (UCHL1), cell-free DNA, and proteins, are useful for the diagnosis of lung cancer." (PMID 34944923, 2021). "It has been described that the over expression of UCHL1 exists in more than half of the lung cancers." (PMID 29765063, 2018). "The expression levels of UCHL1 correlate with those of HIF-1α and are strongly associated with the poor prognosis of breast and lung cancer patients." (PMID 25615526, 2015). "We confirmed that UCHL1 expression levels in malignant tumours correlated with the poor prognosis of patients with breast and lung cancers." (PMID 25615526, 2015). "UCHL1, also called protein gene product 9.5 (PGP9.5) has been identified as an autoantigen in lung cancer patients." (PMID 25610811, 2014). "The cluster 4 had two-lung cancer related genes ubiquitin thiolesterase (UCHL1) and Lactotransferrin (LTF)." (PMID 23122428, 2012). "This was reversed during the lung cancer condition where UCHL1 up-regulated and the LTF highly down-regulated." (PMID 23122428, 2012). "For instance, UCHL1 in lung carcinomas (likewise in larynx carcinomas) was strongly expressed in 7 out of 25 tumor samples (28%), while it was completely undetectable in the normal counterpart." (PMID 21283576, 2011). "UCHL1 participates in the early transformation and tumorigenesis of lung epithelial cells, and serum ELAVL4 levels are significantly higher in patients with lung cancer, indicating their diagnostic relevance." (PMID 39661479, 2025). "Moreover, high expression levels of both UCHL1 and HIF-1α (+++ and ++) were strongly associated with the poor overall survival of lung cancer patients." (PMID 25615526, 2015). "UCHL-1 is overexpressed in pancreatic endocrine tumors, as well as in colorectal and lung cancers." (PMID 26514209, 2015). "In addition, another study on lung cancer suggested that UCHL1 expression is significantly upregulated in non-small-cell-lung cancer cells and it notably enhanced tumor invasion and metastasis in both in vitro and in vivo models through activation of AKT pathway." (PMID 37815895, 2023).
lung carcinoma (continued). "O-acyl oxime isatins were the first reported small molecule inhibitors of UCHL1 activity and promoted the proliferation of UCH-L1-expressing lung cancer and neuroblastoma cells, suggesting that the effect of UCHL1 is antiproliferative in these cells." (PMID 29039082, 2017). "The importance of UCHL1 in the stabilization of HIF-1α and resultant activation of HIF-1 was also validated in clinical human tumours; the expression levels of UCHL1 correlated well with those of HIF-1α in both breast and lung cancers." (PMID 25615526, 2015). "Our data suggest that UCHL1 can be an important player in the synthesis of extracellular matrix, although then most likely in lung cancer and not yet clear in normal (airway) epithelium." (PMID 38016026, 2023). "For example, β3-tubulin and PGP9.5 (also known as UCHL1) are expressed in breast, melanoma and prostate cancer cells, and mature neuron markers, including MAP2 and MAPT, are expressed in breast, gastric and lung cancer cells." (PMID 36621886, 2023). "In addition to UCHL1-expressing prostate cancer cells and HEK293T cells, we are in the process of characterizing other cell types including lung cancer and medulloblastoma cell lines." (PMID 29126443, 2017).
Alzheimer disease (38 papers, 2010 to 2026). A progressive, neurodegenerative disease characterized by loss of function and death of nerve cells in several areas of the brain leading to loss of cognitive function such as memory and language. "In a study of the membrane fraction of post‐mortem frontal cortex tissue, UCHL1 was found to be increased in abundance in Alzheimer's disease, indicating disease relevance of cytosolic versus membrane‐association." (PMID 38087504, 2024). "According to some previous studies, UCHL1 expression significantly increases in some cancer cells and decreases in the brains of Parkinson’s and Alzheimer’s disease patients." (PMID 36830563, 2023). "In contrast, overexpression of UCHL1/PGP9.5 was documented as protective factor, which delays progression of Alzheimer disease." (PMID 30148172, 2018). "By suppressing intrinsic apoptosis, UCHL1 ameliorates type 2 diabetes and Alzheimer’s disease." (PMID 33919439, 2021). "In a mouse model of Alzheimer’s disease, UCHL1 expression was downregulated during ischemic injury." (PMID 33919439, 2021). "On the other hand, UCHL1 and clusterin have been described as important enhancers of neuroprotection and neurogenesis (e.g., neuronal process formation, elongation, and plasticity) as well as a potential target into some neurodegenerative disorders such as Alzheimer’s disease." (PMID 26204925, 2015).
neuroblastoma (23 papers, 1997 to 2025). Neuroblastoma (NB) is the most common solid, extracranial childhood tumor. "The second neural marker, UCHL-1 (alias PGP9.5), is a unique brain-specific deubiquitinating enzyme upregulated also in neuroblastoma, acute lymphoblastic leukemia, non-small cell lung cancer, and renal cell carcinoma." (PMID 34572907, 2021). "Chemical footprinting combined with functional validation in murine neuroblastoma cells identified a short hairpin as key structural determinant for the ability of AS Uchl1 to increase translation." (PMID 29453387, 2018). "In addition, we conducted further experiments to measure the phosphorylation of Akt on serine 473 by manipulating UCHL1 in various cell lines, including neuroblastoma (SH-SY5Y), mouse embryonic fibroblasts (MEF), and hepatocellular carcinoma (SNU398)." (PMID 38212312, 2024). "USP14, HAUSP, and UCHL1 have been identified as key regulators of neuroblastoma differentiation and may play a critical role in neuroblastoma pathogenesis." (PMID 37170124, 2023). "In cancer-related studies, LDN-57444 was used to identify a role for UCHL1 as a prognostic marker in neuroblastoma cell differentiation, and there have even been attempts to formulate this compound to improve its aqueous solubility in order to treat invasive carcinomas." (PMID 34497382, 2022). "We further demonstrated that high UCHL1 expression was associated with NB differentiation, indicated by higher UCHL1 expression in ganglioneuroblastomas/ganglioneuromas and well-differentiated NB than poorly differentiated NB, and the positive correlation between UCHL1 and differentiation markers." (PMID 30359286, 2018). "LDN-57444 has been widely used to inhibit UCHL1 in several type of cancers in which UCHL1 may be expressed, such as in oral squamous cell carcinoma (OSCC), neuroblastoma, non-small cell lung cancer (NSCLC) and invasive carcinomas." (PMID 34497382, 2022). "To investigate invSINEB2-ΔSL1 activity when embedded in full length AS Uchl1, we took advantage of murine neuroblastoma Neuro2a cells, as they express Uchl1 mRNA but do not contain detectable levels of endogenous AS Uchl1." (PMID 29453387, 2018).
colorectal cancer (20 papers, 2006 to 2026). A primary or metastatic malignant neoplasm that affects the colon or rectum. "UCHL1 overexpression as found in colorectal cancer, non-small cell lung carcinoma and RCC was associated with a more aggressive potential and/or metastatic phenotype as well as in some cases with a poor prognosis of the respective patient collectives." (PMID 19857250, 2009). "Moreover UCHL1 expression in cancer-associated fibroblasts of colorectal cancer was found to be an independent prognostic factor for overall and recurrence-free survival." (PMID 21283576, 2011). "UCHL1 demonstrated dual roles in different tumors: as an oncogene in lymphoma, colorectal cancer and B-cell, as a tumor suppressor in nasopharyngeal carcinoma, PCa, and ovarian cancer." (PMID 38918720, 2024). "Perhaps more importantly, previous study found that UCHL1 promotes progression of colorectal cancer cell lines via the activation of CCND2, which is a downstream target of the Wnt β-catenin/TCF pathway." (PMID 34257568, 2021). "UCHL1 is a colorectal cancer oncogene that activated the β-catenin/TCF pathway through its deubiquitinating activity." (PMID 27534621, 2016). "UCHL1 acts as an oncogene and is found to be related to lymph node metastasis in colorectal cancer." (PMID 23637989, 2013). "UCHL1 methylation has been reported in multiple tumors, such as esophageal, gastric, renal, prostate, head and neck squamous, ovarian, hepatocellular and colorectal cancers." (PMID 22028813, 2011). "With respect to a possible function of UCHL1 in ciliated cells in lung airway epithelium, for comparison, when looking to other cell types, UCHL1 is also highly expressed in liver myofibroblasts, cultured dermal fibroblasts from colorectal cancer and human cutaneous wounds." (PMID 38016026, 2023). "UCHL1 inhibition could also be a potential treatment for several types of other cancers where UCHL1 is frequently overexpressed, including prostate cancer, non-small cell lung carcinoma, pancreatic cancer, leukemia, colorectal cancer and medullary thyroid carcinoma." (PMID 34497382, 2022).